HOXC11 (homeobox C11)
Description:
Sequence-specific transcription factor which is part of a developmental regulatory system that provides cells with specific positional identities on the anterior-posterior axis. Binds to a promoter element of the lactase-phlorizin hydrolase gene.
Synonyms: HOX3H
Tractability: PROTAC: UniProt records ubiquitination sites on it; ubiquitination databases record sites on it.
Gene: Protein-coding gene on chromosome 12 (53,973,126 to 53,977,643, forward strand). Ensembl gene ENSG00000123388.
Subcellular location: Nucleus
Subcellular location (Human Protein Atlas): Nucleoplasm; Cytosol
Pathways (Reactome):
Developmental Biology: Formation of the ureteric bud
Gene Ontology:
Molecular function: DNA-binding transcription activator activity, RNA polymerase II-specific; protein binding; RNA polymerase II cis-regulatory region sequence-specific DNA binding; sequence-specific double-stranded DNA binding; DNA-binding transcription factor activity, RNA polymerase II-specific; DNA binding
Biological process: positive regulation of transcription by RNA polymerase II; embryonic skeletal joint morphogenesis; endoderm development; regulation of transcription by RNA polymerase II; regulation of DNA-templated transcription
Cellular component: nucleoplasm; chromatin; nucleus
Genetic constraint (gnomAD): Loss-of-function variants: 17 observed, 22.85 expected, observed/expected ratio (o/e) 0.74, 90% interval 0.51 to 1.12. The upper end of that interval is the gene's LOEUF score, 1.12, which puts it in group 4 of 6, group 1 being the genes least tolerant of losing a copy. Missense variants: 397 observed, 403.33 expected, observed/expected ratio (o/e) 0.98, 90% interval 0.91 to 1.07. Synonymous variants: 188 observed, 185.24 expected, observed/expected ratio (o/e) 1.01, 90% interval 0.9 to 1.14.
Homologues: Orthologues: chimpanzee HOXC11 (99% identical), macaque HOXC11 (98% identical), guinea pig HOXC11 (98% identical), mouse Hoxc11 (98% identical), rat Hoxc11 (98% identical), pig HOXC11 (97% identical), rabbit HOXC11 (97% identical), dog HOXC11 (96% identical), zebrafish hoxc11a (67% identical). Paralogues in human: HOXA11 (51% identical), HOXD11 (45% identical), HOXA13 (24% identical), HOXD10 (23% identical), HOXD9 (22% identical), HOXB13 (21% identical), HOXA10 (21% identical), HOXC9 (20% identical), HOXB9 (20% identical), HOXC13 (20% identical), HOXD13 (20% identical), HOXC10 (19% identical), and 30 more.
Diseases named in the same sentence as HOXC11 in open-access papers:
HOXC11 is named in the same sentence as 42 diseases in open-access papers, as found by Europe PMC text mining. Sharing a sentence is not in itself a finding about the gene and the disease. The quoted sentences say what the papers report.
breast carcinoma (13 papers, 2011 to 2024). "The upregulation of PSAP gene expression by HOXC11 in endocrine-resistant breast cancer cells was of interest primarily due to its association with tamoxifen resistance, but also because of its potential as an AR activator." (PMID 26341737, 2015). "HOXC11 is a regulator of cellular development, and SRC-1 cooperates with HOXC11 to promote the expression of the calcium-binding protein S100beta in endocrine-resistant breast cancer cells." (PMID 38553750, 2024). "In breast cancer, HOXC11 couples with steroid receptor coactivator 1 to inhibit the expression of differentiation protein CD24 and apoptosis protein PRKC apoptosis WT1 regulator (PAWR) function from promoting the progression of breast cancer." (PMID 36823149, 2023). "HOXC11 activates androgen receptors by activating prosaposin, producing more aggressive and endocrine therapy-resistant breast cancer cells when estrogen signaling is blocked." (PMID 36823149, 2023). "For example, HOXC11 was identified to be an indicator of poor response to hormonal therapy in breast cancer cases." (PMID 34712617, 2021). "Taken together, these molecular studies provided us with a model of S100β production in endocrine resistant breast cancer where endocrine treatment can induce rapid tyrosine kinase signaling to induce HOXC11/SRC-1 transcriptional activation of S100β." (PMID 28399921, 2017). "This notion is appealing because HOXC11 promotes breast cancer and the importance of PRC2 to HOTAIR functions has been challenged recently." (PMID 28846832, 2017). "We previously identified HOXC11 to be an indicator of poor response to hormonal therapy in breast cancer." (PMID 26341737, 2015). "RNA-seq experiments identified 1,919 DEGs when HOXC11 was silenced in endocrine-resistant breast cancer." (PMID 26341737, 2015). "To further our understanding of HOXC11 and the role it plays in the development of endocrine resistance and steroidal adaptability we undertook an RNA-seq experiment to identify HOXC11 target genes in resistant breast cancer." (PMID 26341737, 2015). "RNA-sequencing paired with transcription factor motif-mapping was utilised to identify putative HOXC11 target genes in endocrine resistant breast cancer." (PMID 26341737, 2015). "Analysis of TCGA breast cancer dataset showed there to be a weakly positive correlation between HOXC11 and PSAP mRNA only in the luminal B subtype (rs 0.24)." (PMID 26341737, 2015). "In this current study we wanted to further elucidate the role of HOXC11 with regard to endocrine resistance and steroidal adaptability in breast cancer." (PMID 26341737, 2015). "Recently, we and others have described a role for HOXC11 in the transcriptional regulation of S100beta in breast cancer and neuronal tissue." (PMID 21654685, 2011). "More recently, in breast cancer, we have reported a role for HOXC11 in conjunction with the transcriptional activator SRC-1, in the regulation of S100beta." (PMID 21654685, 2011). "We have previously reported that HOXC11 can utilise the steroid receptor coactivator protein to drive tumour progression in breast cancer patients." (PMID 21654685, 2011). "Moreover, HOXC11 is found to be closely correlated with the survival of patients with renal cell cancer, cervical cancer or breast cancer, and serves as a therapeutic target." (PMID 31379707, 2019). "Previous work from this laboratory investigating endocrine resistance in breast cancer has shown the developmental transcription factor HOXC11 to be a strong predictor of metastasis and poor disease-free survival (DFS), independent of receptor status, tumour size, nodal status and grade." (PMID 26341737, 2015). "Briefly, SRC-1 promotes the transcriptional activityof several transcription factors, including HOXC11, PEA3, AP-1, HIF1α, c-FOS, Ets1/2, and STAT1/3, in breast cancer." (PMID 38553750, 2024).
breast carcinoma (continued). "The combination of NCOA1 and the transcription factor HOXC11 can activate the transcription of downstream genes, including integrin α5, ADAM22, and Myc, and can thus promote the metastasis and progression of breast cancer." (PMID 37509133, 2023). "In total, seven TFs (HOXC11, FOXA1, SPDEF, SOX12, HOXC10, GATA3 and TFAP2A) were annotated to the breast cancer samples." (PMID 34712617, 2021). "In our AI-resistant breast cancer model we have shown that PSAP is capable of upregulating and activating AR in the context of high HOXC11 expression." (PMID 26341737, 2015). "HOXC11 and PSAP mRNA levels are strongly correlated in a primary breast cancer cohort (rs = 0.7692, n = 51)." (PMID 26341737, 2015). "Further analysis of TCGA datasets also demonstrate a correlation between HOXC11 and PSAP transcript levels, specifically in luminal B breast cancer in which AR is elevated (rs = 0.46)." (PMID 26341737, 2015). "Homeobox C11 gene (HOXC11), one member of the HOX family, was shown to be closely related to the clinical outcome of patients with renal cancer, cervical cancer or breast cancer." (PMID 35155451, 2021). "We chose posterior HOXC genes HOXC11-13 located in close proximity to the HOTAIR transcript and posterior HOXD genes HOXD10-13, reported to be regulated by HOTAIR in normal fibroblasts and breast cancer mediating aggressive phenotype." (PMID 25994132, 2015).
gastric cancer (4 papers, 2015 to 2021). A primary or metastatic malignant neoplasm involving the stomach. "Interestingly, we identified a novel potential oncogene HOXC11 in gastric cancer pathogenesis with differential expression in gastric cancer tissues by association analysis with candidate gene strategy." (PMID 26384301, 2015).
glioma (4 papers, 2015 to 2023). A benign or malignant brain and spinal cord tumor that arises from glial cells (astrocytes, oligodendrocytes, ependymal cells). "Many HOMEOBOX (HOX)-related genes (HOXD11, HOXD9, HOXC10, HOXC11, HOXC6, HOXB3, HOXA2, HOXA1) were associated with a glioma grade and significantly overexpressed in GIV (Wilcoxon rank-sum and BH padj < 0.05)." (PMID 36850002, 2023). "The upregulation of HOXA9, HOXC6, HOXC11, HOXD1, and HOXD8 expression is associated with the proliferation and growth of glioma." (PMID 26565624, 2015). "However, the molecular mechanisms of HOXC11, HOXC9, ELF5, and HNF4A function in the development and progression of gliomas remain unclear and require further exploration in the future." (PMID 33503296, 2021).
malignant melanoma (4 papers, 2011 to 2024). "The upregulated HOXC11 is also a transcription factor, regulating the expression of linage marker S100b in melanoma." (PMID 35269844, 2022). "HOXC11 recruitment to the promoter of S100beta was observed in the primary melanoma cell line SKMel28." (PMID 21654685, 2011). "Using chromatin immunoprecipitation, we established HOXC11 recruitment to the promoter of S100beta in primary melanoma cells." (PMID 21654685, 2011). "SRC-1 and its partner HOXC11 are highly expressed in malignant melanoma, and SRC-1 can cooperate with HOXC11 to promote the expression of S100beta, which is a stimulating factor for cell proliferation and migration and an inhibitor of cell apoptosis and differentiation." (PMID 38553750, 2024). "Additionally, dasatinib, an ATP-competitive dual Src/Abl inhibitor, could reverse SRC-1-mediated melanoma progression by suppressing the interaction between HOXC11 and SRC-1." (PMID 38553750, 2024). "In this study, we used combined immunohistochemical and immunofluorescence to assess expression of HOXC11 and its coactivator protein SRC-1 in benign nevi and malignant melanoma." (PMID 21654685, 2011). "The ATP-competitive dual Src/Abl inhibitor dasatinib inhibited HOXC11 and SRC-1 mediated S100beta production in malignant melanoma cells." (PMID 21654685, 2011). "Using a variety of molecular and cellular techniques, we established a role for both HOXC11 and SRC-1 in the regulation of S100beta, uncovering a new mechanism of S100beta regulation in melanoma." (PMID 21654685, 2011). "We found high levels of expression and coassociation of HOXC11 and SRC-1 in malignant melanoma in comparison with benign nevi." (PMID 21654685, 2011). "Immunoprecipitation studies confirmed HOXC11 and SRC-1 interaction in primary (SKMel28) and malignant (MeWo) melanoma cell lines." (PMID 21654685, 2011). "Greater protein expression of both HOXC11 and SRC-1 were found in metastatic melanoma cells in comparison with primary melanoma cell lines." (PMID 21654685, 2011). "Combined immunohistochemical and immunofluorescence was used to assess the expression of HOXC11 and its coactivator protein SRC-1 in benign nevi and malignant melanoma." (PMID 21654685, 2011). "In cutaneous melanomas, Src-1 increases S100β expression by serving as a coactivator for HOXC11, and high expression of Src-1 and HOXC11 was found in malignant melanoma but not in benign nevi." (PMID 30973923, 2019). "Expression levels of the transcription factor HOXC11 and its coactivator SRC-1 were significantly elevated in malignant melanoma in comparison with benign nevi (P<0.001 and P=0.017, respectively, n=80), and expression of HOXC11 and SRC-1 in the malignant tissue associated with each other (P<0.001)." (PMID 21654685, 2011). "We investigated whether inhibition of the Src kinase signalling network could have a role in disrupting the functional interaction between HOXC11 and SRC-1 in melanoma cells." (PMID 21654685, 2011). "In line with our observation of increased expression and interaction between HOXC11 and SRC-1 in malignant melanoma versus benign nevi, high expression levels of their putative target S100beta were detected in melanoma tissue in comparison with little or no expression in the naevus tissue." (PMID 21654685, 2011).
cervical cancer (3 papers, 2017 to 2021). A primary or metastatic malignant neoplasm involving the cervix. "In this study, we showed that the increased mRNA expression of four HOX genes—HOXA1, HOXA5, HOXA6, and HOXC11—is independently associated with mortality in cervical cancer based on data from TCGA." (PMID 29137433, 2017).
colon adenocarcinoma (3 papers, 2021 to 2023). "It is known that HOXC11 plays a tumor-suppressing role in human non-small cell lung cancer cells, whereas it plays a tumor-promoting role in renal clear cell carcinoma and colon adenocarcinoma." (PMID 34515615, 2021). "HOXC11 positively regulates the lncRNA HOTAIR and is associated with poor prognosis in colon adenocarcinoma (COAD)." (PMID 36924407, 2023).
non-small cell lung carcinoma (3 papers, 2020 to 2022). A group of at least three distinct histological types of lung cancer, including non-small cell squamous cell carcinoma, adenocarcinoma, and large cell carcinoma. "The overexpression of hsa_circ_0075542 increased the protein levels of HOXC11, which is the direct target of miR-1197 in human non-small cell lung cancer cells." (PMID 34515615, 2021). "For example, downregulated miR-1197 can inhibit the progression of human non-small-cell lung cancer by upregulating HOXC11." (PMID 32908877, 2020). "For example, miR-1197 controls the progression of non-small-cell lung carcinoma through regulating MADD, and also promotes cell proliferation by upregulating HOXC11." (PMID 34986861, 2022).
acute myelocytic leukemia (2 papers, 2015 to 2023). "In acute myeloid leukaemia (AML), fusion proteins of NUP98:HOXC11 and NUP98:HOXD13 have been identified which result in aberrant HOX trans-regulatory activity." (PMID 25860510, 2015).
clubfoot (2 papers, 2023 to 2025). The most common congenital deformation of the foot, occurring in 1 of 1,000 live births. "Recent findings have also highlighted HOXC microdeletions overlapping a noncoding region upstream of HOXC13, alongside a point mutation in HOXC11 segregating within a family affected by isolated clubfoot, and another point mutation in HOXC12 that is prevalent among clubfoot patients." (PMID 40746736, 2025). "A missense SNP in HOXC11 in a family with an isolated form of clubfoot and a missense SNP in HOXC12 in clubfoot patients have been reported." (PMID 37964341, 2023).
colorectal cancer (2 papers, 2025). A primary or metastatic malignant neoplasm that affects the colon or rectum. "HOXC11 is overexpressed in colorectal cancer (CRC) and lung adenocarcinoma (LUAD) and is associated with poor patient prognosis." (PMID 40302809, 2025). "Previous studies in lung, breast, and colorectal cancers have shown that aberrant HOXC11 activity disrupts normal cell cycle regulation, DNA repair, and apoptosis, thereby promoting unchecked cell proliferation and tumor progression." (PMID 41037214, 2025).
pancreatic cancer (2 papers, 2018 to 2025). "In PDAC, aberrant expression of several HOX transcription factors has been described and functional studies have shown that HOXA10, HOXB7, and HOXC11 promote pancreatic cancer development while HOXA1, HOXB1, and HOXB3 act as tumor-suppressors." (PMID 40619489, 2025).
prostate carcinoma (2 papers, 2021 to 2025). A carcinoma that arises from epithelial cells of the prostate gland. "Overexpression of miR-1197 decreased the protein level of HOXC11, supporting that miR-1197 targeted HOXC11 in prostate cancer cells." (PMID 34515615, 2021). "HOXC11, a highly conserved transcription factor, is involved in prostate cancer progression, potentially regulated through the hsa_circ_0075542/miR-1197 axis, where miR-1197 promotes tumorigenesis, and HOXC11 may mediate its effects on malignancy." (PMID 40297177, 2025). "At present, the role of HOXC11 in prostate cancer cells has not been discussed." (PMID 34515615, 2021).
bladder cancer (1 paper, 2023). "The expression of HOXC4, HOXC5, HOXC6, and HOXC11 was detected in 60%, 86%, 100%, and 80% of bladder cancer tissues, respectively." (PMID 37627900, 2023). "Four genes (HOXC4, HOXC5, HOXC6, and HOXC11) located at the HOX C locus as well as one gene (HOXD11) located at the HOX D locus were not expressed in normal bladder tissues but expressed in most bladder cancer tissues." (PMID 37627900, 2023).
breast tumour (1 paper, 2015). "Transcript levels of HOXC11 and PSAP correlated strongly in samples of primary breast tumours (r = 0.7692, n = 51)." (PMID 26341737, 2015). "Transcript levels of HOXC11 and PSAP mRNA were found to correlate significantly in primary breast tumour tissue (rS = 0.7745, p <0.0001)." (PMID 26341737, 2015).
carcinoma of the lip (1 paper, 2022). "HOXA5, HOXB9, HOXC8, HOXC10, and HOXC11 genes were specific to certain sites of the oral cavity whereas HOXA10 was associated with the development of the carcinoma of the lip and oral cavity." (PMID 35710803, 2022).
gastric adenocarcinoma (1 paper, 2023). "A previous bioinformatics analysis revealed that HOXC genes (HOXC8, HOXC9, HOXC10, HOXC11, HOXC12, and HOXC13) might participate in pathogenesis of gastric adenocarcinoma." (PMID 37724126, 2023).
invasive breast carcinoma (1 paper, 2022). A carcinoma that infiltrates the breast parenchyma. "We identify early processes and potential biomarkers, including CAMK2N1, MNX1, ADCY5, HOXC11 and ANKRD22, whose reduced expression is associated with the progression of DCIS to invasive breast cancer." (PMID 35697697, 2022).
lung carcinoma (1 paper, 2023). "At the same time, we explored the regulatory mechanism of HOXC11 in lung cancer to outline its role of HOXC11." (PMID 36823149, 2023). "Kaplan-Meier Plotter lung cancer dataset was used to analyze the relationship between mRNA expression of HOXC11 and overall survival (OS) of lung cancer patients." (PMID 36823149, 2023). "Based on this, we analyzed the expression of HOXC11 in the lung cancer database and explored the effect of HOXC11 on the biological function of LUAD cells." (PMID 36823149, 2023). "HOXC11 has a lower mRNA level in paracancerous tissues than in lung cancer tissues, including LUAD or LUSC." (PMID 36823149, 2023). "By exploring the expression of HOXC11 in the TCGA database and clinical samples of lung cancer, we found that HOXC11 mRNA levels were upregulated in both LUAD and LUSC." (PMID 36823149, 2023). "Apart from this, there is still a gap in reports on the distinct role of HOXC11 in lung cancer, which has aroused our interest in conducting further studies." (PMID 36823149, 2023). "Meanwhile, we also identified a downstream target of HOXC11 and preliminarily verified its function in lung cancer cells." (PMID 36823149, 2023). "To investigate whether HOX gene expression in lung cancer is similarly affected by IKKα as in skin cells described in Introduction, we explored HOXC11 and IKKα expression in NSCLC cells." (PMID 36823149, 2023). "Moreover, its expression in lung cancer was regulated by IκB kinase α (IKKα), a pivotal kinase in NF-κB signaling, which was related to the ubiquitination of HOXC11." (PMID 36823149, 2023). "Therefore, we conclude that HOXC11 impacts the development of LUAD and facilitates lung cancer progression by promoting the expression of SPHK1." (PMID 36823149, 2023).
lymph node metastasis (1 paper, 2017). "Overall mortality was significantly associated with advanced FIGO stage, lymph node metastasis, lymphovascular invasion, and increased HOXA1, HOXA5, HOXA6, and HOXC11 mRNA expression." (PMID 29137433, 2017).